KRAS (KRas proto-oncogene, GTPase)
Diseases named in the same sentence as KRAS in open-access papers (continued):
Sharing a sentence is not in itself a finding about the gene and the disease.
tumor (continued). "We also assayed for mutations in KRAS and BRAF to determine the prevalence of coincident GNAS/KRAS or GNAS/BRAF mutations in our tumor cohort." (PMID 24498230, 2014). "KRAS and BRAF mutations were analysed by pyrosequencing in tumours from 494 incident CRC cases in the Malmö Diet and Cancer Study." (PMID 24918610, 2014). "We briefly discuss the tumor-suppressive role of miRNAs that target and regulate KRAS and the regulation of those miRNAs." (PMID 25433809, 2014). "In the case of KRAS, we observed significant mutant allele overexpression in three out of five mutated samples, with another sample showing borderline significance, suggesting that the overexpression might be the result of positive selection in tumor evolution." (PMID 25315065, 2014). "KRAS mutation (codon 2) was noted more frequently in LST (13/36, 36.1%) than polypoid neoplasms (5/34, 14.7%, p = 0.041)." (PMID 25551625, 2014). "KRAS mutations represent an early genetic event in PDAC pathogenesis and, as regards solid lesions, it is considered a tumor marker for pancreatic adenocarcinoma." (PMID 24504548, 2014). "To test if the inhibition of tumorigenicity by miR-126 also occurs in vivo, we transfected HCT116 KRAS-Mutant cells with siCTL or miR-126 mimics for 48 h and generated xenografts in athymic nude mice; tumor volumes were assessed after 9 days." (PMID 25245095, 2014). "The overall frequency of KRAS and BRAF mutations in our tumor population was approximately 56% (44% KRAS, 12% BRAF), which is in agreement with previous studies." (PMID 24498230, 2014). "While it has been reported that KRAS is regulated by several tumor suppressor miRNAs, this is the first report on the direct regulation of KRAS by miR-200c." (PMID 24368337, 2014). "We previously used a transgenic mouse expressing an inducible form of the kRas oncogene under control of the mouse mammary tumor virus (MMTV) promoter to observe tumor development in vivo in the post-pubertal mammary gland." (PMID 25473842, 2014). "While it has been reported that KRAS is modulated by several tumor suppressor miRNAs, this is the first report on the regulation of KRAS by miR-200c, both playing a pivotal role in oncogenesis." (PMID 24368337, 2014). "Considering the final endpoint, using ASLNAqPCR we detected a KRAS mutation in the 56.8% of adenocarcinomatous and pre-neoplastic lesions (in the 60% of PDAC, 41.7% of IPMNs and in the 66.7% of inoperable neoplasias." (PMID 24504548, 2014). "Mutations in KRAS, NRAS, or BRAF (all upstream of the MEK complexes) are very common in CRC, and have been found in 50–60% of tumor samples." (PMID 25401499, 2014). "Tumors of animals harboring hamartin loss and KRAS (G12D) expression in lung epithelial cells revealed 1) reduced tumor latency, 2) an activation of mTOR and 3) a response to treatment with rapamycin with improved survival compared to KRAS alone mutant mice." (PMID 24593867, 2014). "Nine GNAS mutant tumors (90%) harbored concomitant activating mutations in either the KRAS or BRAF oncogene, which was significantly greater than the mutation frequency of these genes in the tumor population (56%, p<0.0305)." (PMID 24498230, 2014). "A significant interaction of KRAS status and primary tumor location concerning OS and PFS was observed." (PMID 24816724, 2014). "Among patients with a KRAS wild type tumor, the median OS for non-users compared to statin users was 22.4 vs. 19.8 months (p = 0.650), in patients with a KRAS mutant tumor the median OS was 18.1 vs. 14.5 months (p = 0.125), respectively." (PMID 25375154, 2014). "At this study the different effect of a KRAS mutation in MS-L/MSS and MSI-High tumours was consistent with the concept that these are different forms of CRC." (PMID 25361007, 2014).
tumor (continued). "Our findings confirm that genetic alterations that occur early in colorectal carcinogenesis, namely mutations in APC, KRAS, NRAS, and BRAF, persist through tumor evolution and show an exceedingly high level of concordance between primary tumor and metastases." (PMID 25164765, 2014). "As already reported for these neoplasms, BPDCN also shows a clear predominance of NRAS mutations over KRAS mutations." (PMID 25115387, 2014). "MDM4 expression occurs when tumor cells have acquired MDM4 amplification, activated KRAS mutations, or loss of miR-34a-mediated suppression." (PMID 25621298, 2014). "Here we show that IKKβ inhibition by CmpdA treatment affected the microenvironment of KRAS-induced lung tumors, reducing tumor-related inflammation and angiogenesis." (PMID 24955217, 2014). "Several assays for KRAS and BRAF mutations have been developed that involve DNA extraction from a single tumor tissue block, followed by a mutation-specific, polymerase chain reaction (PCR)-based assay or the sequencing of the relevant codons." (PMID 24765171, 2014). "We show that treatment with P7170 results in a marked reduction in the survival of NSCLC cells with different mutations in EGFR, KRAS, PIK3CA, or PTEN and inhibition of tumor growth in vivo." (PMID 25466244, 2014). "The results from this prospective cohort study further support an influence of sex and lifestyle factors on different pathways of colorectal carcinogenesis, defined by KRAS and BRAF mutation status of the tumours." (PMID 24918610, 2014). "Specifically, mitochondrial oxidants are increased in cancer, including KRAS driven lung tumors, and support proliferation and metastasis of tumor cells." (PMID 25462069, 2014). "The effect of primary tumor location on OS in patients with BRAF V600E mutant tumors seemed consistent with the observation in the KRAS codon 12/13 wild-type cohort." (PMID 24816724, 2014). "KRAS genotyping highlights the value of banking tumor specimens obtained from primary tumors or a metastasis." (PMID 24884535, 2014). "In another study, patients with p.G13D-mutated tumours have a worse OS in patients with advanced and recurrent CRC than tumours with either KRAS wt or bearing another KRAS mutations." (PMID 25361007, 2014). "A recent literature review confirmed that KRAS alterations in ctDNA from plasma are significantly predictive of KRAS tumor status with a concordance between tumor and plasma status ranging from 29% to 100%." (PMID 25491325, 2014). "The receptor tyrosine kinases EGFR and ERBB2, the GTPases KRAS, NRAS, and HRAS, and the kinase BRAF are frequently mutated in cancers and can drive tumor proliferation." (PMID 24874471, 2014). "Targeted sequencing (i.e. codon 599 of BRAF and codons 12 and 13 of KRAS) using a single representative tumor sample from 34/52 (65%) patients revealed a BRAF and KRAS mutation in 2 (6%) and 14 (41%) cases respectively." (PMID 25523272, 2014). "In patients with BRAF mutant mCRC, the effect of primary tumor location seemed again consistent with the effects observed in patients with KRAS codon 12/13 wild-type tumors." (PMID 24816724, 2014). "KRAS mutation as well as CDKN2A methylation level was associated with prognosis and if found within the same tumor turned the prognosis was even worse." (PMID 25261372, 2014). "Subsequently, other tumor-suppressive miRNAs, including miR-96, miR-30c and miR-181a, have shown to regulate KRAS in various cancers." (PMID 25433809, 2014). "In most tumour types exhibiting mutation of a RAS gene family member (HRAS, KRAS, or NRAS), the mutational activation of one member predominates." (PMID 25361007, 2014).
tumor (continued). "Bisulfite sequencing analysis of representative CIMP marker genes confirmed promoter hypermethylation in all KRAS-positive CRC tumor samples." (PMID 24623306, 2014). "In Cancer models: The identification of mutationally activated KRAS and BRAF alleles in several tumour models supports the importance of this signalling pathway in cancer progression." (PMID 25361007, 2014). "We collected formalin-fixed, paraffin-embedded and fresh frozen tumor samples from AGC patients and analyzed the KRAS, NRAS, BRAF and PIK3CA mutations by direct-sequencing." (PMID 24774510, 2014). "Mutant KRAS caused an increase in the levels of these two proteins, which in turn caused the elevated ZNF304 levels and the excessive marking of the DNA in the tumor suppressor genes." (PMID 24623306, 2014). "We analyzed the prognostic–predictive relevance of KRAS status, determined in tumor and plasma DNA by two different assays, in a large mono-institutional series of mCRC patients." (PMID 25491325, 2014). "DNA sequencing and peptide-nucleic-acid-mediated-polymerase chain reaction clamping (PNA-PCR) were used to determine KRAS status in 416 tumor and 242 matched plasma DNA samples from mCRC patients who received chemotherapy only." (PMID 25491325, 2014). "The results are thus in agreement with our clinical data indicating that both EGFR GCN and KRAS status define the tumor cell response to anti-EGFR mAbs." (PMID 24940619, 2014). "Out of 46 tumors of right-sided origin, 27 tumors were diagnosed with KRAS codon 12/13 wild-type status, while 19 patients presented a KRAS codon 12/13 mutant tumor." (PMID 24816724, 2014). "KRAS mutations are frequently observed in human CRC (42% incidence) and validate our CB42 tumor model as reflective of human disease." (PMID 25162504, 2014). "Statin use alone did not have a statistically significant effect on PFS of cetuximab treated patients with a KRAS mutant tumor." (PMID 25375154, 2014). "The efficacy of the biweekly combination of cetuximab with FOLFOX-4 in patients with wild-type KRAS tumours supports the administration of cetuximab in a dosing regimen more convenient for patients and healthcare providers." (PMID 25417182, 2014). "Using a 85 CRC tumor dataset available through the Cancer Genome Atlas (TCGA at cBioPortal) we compared the expression of miR-126 in CRC tumor samples that were KRAS-WT or KRAS-Mutant." (PMID 25245095, 2014). "It has been suggested that circulating DNA is a suitable and reliable source of DNA for tumor somatic gene alterations, but is this the case for the KRAS gene?" (PMID 25491325, 2014). "We analyzed 242 paired tumor and plasma samples, the largest series reported to date, and showed that determining KRAS status in plasma is feasible and provides information on gene status concordant with tumor DNA analysis by PNA-PCR in 73% of cases." (PMID 25491325, 2014). "Here, DNA extraction was centralized and tumor cell content was validated by 7 independent pathologists therefore only KRAS genotyping methods were compared." (PMID 23935912, 2013). "Here, similar cell lines (4296) and FFPE tumor samples ADNs (1152) were sent to the different participants and 5448 KRAS genotyping results were submitted and analyzed." (PMID 23935912, 2013). "In further study, we aim to analyze KRAS status by using circulating tumor cells, which play a core role in liquid biopsy." (PMID 24304820, 2013). "In transgenic mice, the pancreas-specific and reversible expression of inducible KRAS G12D mutant was shown not only to initiate neoplastic lesions but was also involved in tumor maintenance." (PMID 23565280, 2013). "In genetically engineered mice G12D mutant KRAS is reported to promote widespread colonic epithelia hyperplasia and neoplasia." (PMID 23565280, 2013). "NF-κB signaling has recently been shown to be essential for KRAS driven tumor growth, chemoresistance and radioresistance in NSCLC." (PMID 24143232, 2013).
tumor (continued). "DNA was extracted from micro-dissected paraffin-embedded tumor and analyzed by a PCR-based DNA sequencing method to examine codons 12, 13 and 61 of the KRAS proto-oncogene." (PMID 23391555, 2013). "In multivariate analysis, favourable predictive factors were high AREG mRNA in KRAS wild type tumours, high EREG mRNA, low Ephrin A2 receptor mRNA." (PMID 23374602, 2013). "The percentage of KRAS mutant DNA in tumor cells was calculated as percentage of KRAS mutant DNA in total DNA/percentage of tumor cells in tumor tissue." (PMID 23874486, 2013). "As more and more highly sensitive screening methods are established, more tumor specimens will be classified as KRAS mutant ones." (PMID 23874486, 2013). "Overall, our results indicate that oncogenic KRAS activation in Apc-driven tumours results in the expansion of the CSCs compartment by increasing ®-catenin intracellular stabilization." (PMID 24069241, 2013). "Xenograft model L030, with a KRAS mutation and EGFR wild type gene, showed a minor response to gefitinib treatment (25% tumor growth inhibition (TGI))." (PMID 23842453, 2013). "The present study reports a case of the coexistence of two mutations, p.G12D (GGT>GAT) and p.G12V (GGT>GTT), in the same codon of the KRAS gene, in the same selected tumor area, thus demonstrating the existence of intratumoral heterogeneity." (PMID 23761841, 2013). "The detection of KRAS and BRAF mutations analysis was performed in 94 and 83 tumor tissues, respectively." (PMID 23637996, 2013). "At the tumour level, somatic mutations in EGFR, KRAS, BRAF, PTEN and PIK3CA are associated with poor response to anti-EGFR therapy in CRC." (PMID 24152305, 2013). "While several in vitro studies have demonstrated that KRAS is necessary for maintenance of the neoplastic phenotypes in tumor cell lines, malignant transformation of normal pancreatic epithelial cells by oncogenic KRAS has proven to be more stochastic." (PMID 24386371, 2013). "Our results indicated that the percentage of KRAS mutant DNA in tumor cells varied from 10.8% to 98.3% and this distribution was continuous." (PMID 23874486, 2013). "Indeed, a large number of oncogenes (e.g., ERBB2, MYCN, KRAS, etc.) are amplified at the level of the genome within various tumor types and this amplification not only underlies hypermorphic expression and/or function, but also serves to differentiate the tumor cells from normal surrounding tissues." (PMID 24202319, 2013). "Gefitinib anti-tumor efficacy in these patient-derived NSCLC xenografts containing EGFR and KRAS mutation was consistent with the reported results from previous clinical trials." (PMID 23842453, 2013). "In the presence of wild-type KRAS, high AREG mRNA levels were independently associated with 83.0% reduction in the risk of death compared to patients with AREG-low tumours." (PMID 23374602, 2013). "Individual tumor samples correct calls ranged from 100% to 76.6%, indeed all laboratories correctly genotyped 16/24 samples and one sample (a KRAS p.G12A sample) generated mistakes by 11 laboratories." (PMID 23935912, 2013). "Then we quantified and calculated the proportion of KRAS mutant DNA in tumor tissues and found that the proportion varied a lot." (PMID 23874486, 2013). "In such study ALI should be compared with tumor specific mutations like EGFR, KRAS, EML4-ALK etc. to see which mutations are associated with higher systemic inflammation." (PMID 23530866, 2013).
tumor (continued). "In the current study all 45 KRAS positive samples were wild-type for BRAFV600E mutation and all 12 BRAF positive samples were wild-type for KRAS, supporting the mutual exclusiveness of the two genes in the tumour process." (PMID 23536897, 2013). "Among KRAS-wild type cases, 81.4% were seen in AREG-high and 57.4% in EREG-high tumours, while of KRAS-mutated cases only 63.9% were observed in AREG-high and only 35.7% in EREG-high tumours." (PMID 23374602, 2013). "KRAS codons 12 and 13, and BRAF mutations were analysed by pyrosequencing of tumours from 525 and 524 incident CRC cases in The Malmö Diet and Cancer Study." (PMID 24020794, 2013). "Concurring with this theory, Navin and colleagues similarly observed that copy number amplification of KRAS, an important oncogene, is unique to aneuploid tumor population." (PMID 23418593, 2013). "There are two possible explanations for the discordant results for KRAS: heterogeneity of KRAS status within the primary tumor, or clonal selection during the process of metastasis." (PMID 24304820, 2013). "We evaluated the assay in 6 different tumor types procured from commercial sources for the assay validation and compared our KBN-SNPE (KRAS, BRAF, NRAS Single Nucleotide Primer Extension) mutation assay results to Sanger sequencing and NGS." (PMID 23991070, 2013). "Remarkably, both KRAS and let-7 are important in cancer development being KRAS a well-known oncogene and let-7 a microRNA that acts as tumor suppressor gene." (PMID 23586049, 2013). "The relative KRAS mRNA expression was significantly higher in tumor tissues than that in non-tumor tissues." (PMID 23425895, 2013). "Yamauchi et al13 recently carried out a study which examined the rates of CIMP, KRAS and BRAF mutations and microsatellite instabilities (MSIs) compared to the location of tumours in the colon or rectum." (PMID 23096130, 2013). "The tumor suppressor roles of miR-433 and miR-127 in GC cells were mediated by inhibition of KRAS and MAPK4, respectively." (PMID 23880861, 2013). "Anti-tumor efficacy studies using gefitinib demonstrated that the EGFR activating mutation model had superior sensitivity and that the KRAS mutation models were resistant to gefitinib." (PMID 23842453, 2013). "The primary objective was to assess the objective response rate (ORR), while EGFR and KRAS mutations and mRNA and protein expression levels of ERCC1 and RRM1 were analyzed in tumor tissues and blood samples." (PMID 23621919, 2013). "Most cases displayed both wild-type and mutant KRAS signals in the tumor cell areas, indicating the presence of a heterozygous mutation and expression of both alleles." (PMID 24280411, 2013). "Compared to AREG, tumour EREG mRNA expession was a stronger predictor of cetuximab benefit in KRAS wild type cases in three more series." (PMID 23374602, 2013). "Patterns of tumor ploidy and allelic imbalances between mutational groups were evaluated by GAP analysis of 141 tumors (n=43 EGFR-mutated, 39 KRAS-mutated, and 59 EGFRwt/KRASwt) profiled by SNP microarrays." (PMID 24205279, 2013). "Regarding KRAS, the same group reported in a pooled dataset of 579 cetuximab-treated CRC patients that those with codon 13 KRAS mutant tumours (G13D) had better outcomes (HR for death 0.50) compared to patients with other KRAS mutant tumours." (PMID 23374602, 2013). "AREG mRNA reflects EGFR signalling in KRAS wild type tumours, predicting for cetuximab efficacy when high and failure when low." (PMID 23374602, 2013). "Among the three RAS genes (H-RAS, KRAS and N-RAS) KRAS is the most commonly activated in human tumours." (PMID 23506169, 2013). "The health authorities regulatory restriction of the prescription of anti-EGFR monoclonal antibodies to wild-type KRAS tumor patients plays a major role in selecting anti-VEGF or anti-EGFR introduction in first-line therapy." (PMID 24133623, 2013).